EGFR (epidermal growth factor receptor)
Diseases named in the same sentence as EGFR in open-access papers (continued):
Sharing a sentence is not in itself a finding about the gene and the disease.
lung cancer (continued). "Although EGFR mutation status could be tested for lung cancer patients to guide therapeutic decision for using EGFR–TKI or not, such biomarker testing may not always be possible or available due to tissue availability or financial constraint." (PMID 23929397, 2013). "The high activity of EGFR protein in lung cancer is due to the activation mutations, but the gene amplifications may also play a significant role." (PMID 23536868, 2013). "Further useful applications may include for example the EGFR signaling pathway (where approximately 2000×2000 combinations of tertiary structures need to be examined), which is implicated in the onset of lung cancer and various other serious diseases." (PMID 24004986, 2013). "This apparent discrepancy between Western and Eastern populations may be due to geographical differences, as shown for the situation with EGFR mutation in lung cancer." (PMID 24088382, 2013). "Screening for EGFR mutation is a key molecular test for management of lung cancer patients." (PMID 23620765, 2013). "Interestingly, in an EGFR mutated lung cancer cell line, treatment with an EGFR inhibitor (Gefitinib) resulted in a concentration specific reduction in c-MYC and miR-9 expression while not changing let-7a expression." (PMID 23365639, 2013). "It is important to emphasize that PCR/sequencing might also lead to false positive results when analyzing small tumor samples, as recently suggested by the results of the Italian external quality assessment for EGFR mutations in lung cancer." (PMID 24364033, 2013). "Notably, the KYSE270 cells were hypersensitive to AG1478 at a sub-micro molar level of IC50 (0.45 μM), which is similar to the hypersensitivity of lung cancer cells harboring an EGFR mutation." (PMID 23426935, 2013). "To accomplish this goal, we experimentally derived a mutant EGFR interactome using disease-specific EGFR isoforms directly in lung cancer cells harboring EGFR mutations and hypersensitive to EGFR inhibitors using tandem affinity purification–liquid chromatography–mass spectrometry (TAP-LC-MS/MS)." (PMID 24189400, 2013). "Furthermore, detection of epidermal growth factor receptor (EGFR) mutations using plasma DNA is essential to determine appropriate lung cancer treatment and monitoring." (PMID 24065096, 2013). "In non-small-cell lung cancer (NSCLC), the increased responsiveness of epidermal growth factor receptor (EGFR) mutation positive cases to EGFR-tyrosine kinase inhibitors, such as gefitinib or erlotinib, represents a landmark finding towards personalized lung cancer care." (PMID 23468851, 2013). "The description of oncogenic mutations (e.g., EGFR mutations) and the introduction of new therapeutics directly targeting these molecular changes (e.g., EGFR TKIs) have changed the therapeutic strategies in lung cancer treatment." (PMID 23802096, 2013). "Moreover, HER2 overexpression and amplification were reported recently to be a potential mechanism of acquired resistance to EGFR inhibition in EGFR mutant lung cancers that lack the second-site EGFR T790M mutation." (PMID 23527257, 2013). "Intratumoral EGFR mutation homogeneity has long been assumed in lung cancers." (PMID 23418425, 2013). "Over-expressing miRNA-7 could radiosensitize A549 lung cancer cells by activating EGFR-associated signaling." (PMID 23614048, 2013). "Icotinib significantly inhibited proliferation of the EGFR-mutated lung cancer HCC827 cells." (PMID 23586056, 2013).
lung cancer (continued). "Thus, it is rational to deduce that EGFR overexpression due to -216G/T variants is likely to promote the pleural metastasis of lung cancer." (PMID 24137392, 2013). "EGFR mutations are now attractive targets for the treatment and prevention of lung cancer." (PMID 24137392, 2013). "Previous reports showed twelve cases of EML4–ALK-positive lung cancer with EGFR mutation." (PMID 23714228, 2013). "The interplay between EGFR and AURKA provides an explanation for the difference in EGF dependency between EGFR-WT and EGFR-mutant cells and may provide a new therapeutic strategy for lung cancer patients carrying EGFR mutations." (PMID 23520446, 2013). "Further studies are needed to determine whether differences in EGFR mutation status detected using methods with different sensitivities are associated with treatment response to EGFR TKIs in lung carcinoma." (PMID 24376508, 2013). "Thus, the pathologic evaluation of a lung carcinoma now requires both an accurate subtyping by histological and immunohistochemical studies as well as the determination of the EGFR mutational status to select patients for TKIs therapy." (PMID 24376723, 2013). "Therefore, according to these data, activating EGFR mutations in lung carcinoma, even in cases with peritoneal disease, are considered positive predictors of anti-EGFR therapy." (PMID 24137394, 2013). "Erlotinib and EGFR mutated lung cancer has also provided significant clinical results." (PMID 25562699, 2012). "Gefitinib (AstraZeneca, UK) is a selective epidermal growth factor receptor (EGFR) tyrosine kinaseinhibitor which has approval in the UK as a first-line treatment of locally advanced or metastatic nonsmall cell lung cancer if they test positive for the EGFR tyrosine kinase mutation." (PMID 23320223, 2012). "In addition, PIK3CA mutations have been detected in a small percentage (~5%) of EGFR mutant lung cancers with acquired resistance to EGFR TKI therapy." (PMID 26316937, 2012). "Restoring miR-145 expression in vitro in EGFR mutated lung cancer cell line could significantly reduce cell proliferation." (PMID 23369397, 2012). "The underlying mechanisms remain unclear, but it may be that intron 1 of EGFR is associated with sensitivity to EGFR TKIs in lung cancer patients, and is correlated with certain biomarkers other than EGFR mutations." (PMID 23226726, 2012). "We report a rare case of lung cancer harboring both EGFR mutation and EML4-ALK fusion gene." (PMID 23181703, 2012). "In summary, the 8227G/A polymorphism of EGFR may influence OS in gefitinib-treated lung cancer patients." (PMID 23226726, 2012). "For lung cancer patients harboring a secondary mutation in EGFR that abrogates EGFR TKI affinity or binding, such as exon 20 insertion, duplication and the T790M substitution, the development of novel EGFR TKIs are needed to more effectively target mutant EGFR." (PMID 22970367, 2012). "However, about 50% of lung cancer patients treated with EGFR-TKI acquire a secondary mutation that confers drug resistance, the T790M (C2369G; ID: rs121434569), located in exon 21 of the gene, which reduces the affinity of the ATP-binding site for the drug." (PMID 23207070, 2012). "In addition to the well-characterized causes of drug resistance in lung cancer patients, elucidation of further mechanism for acquired resistance is essential for the development of new EGFR-targeted drugs." (PMID 22815900, 2012). "The presence of a germline EGFR T790M mutation may be associated with increased risk of developing lung cancer." (PMID 22970367, 2012).
lung cancer (continued). "Furthermore, KRAS and EGFR mutations have been detected in circulating tumour cells from patients with metastatic colon and lung cancer respectively." (PMID 22978632, 2012). "Furthermore, these activating mutations gained addiction to EGFR in lung cancer cells, resulting in enhanced susceptibility to EGFR-TKI such as gefitinib and erlotinib." (PMID 22815900, 2012). "Further study should be required to confirm whether such loss of mutant EGFR gene copy is specifically responsible for acquirement of drug resistance in patients with lung cancer." (PMID 22815900, 2012). "Interestingly, MUC1 expression levels were reported to be associated with response to EGFR inhibitors in lung cancer patients." (PMID 22457794, 2012). "To explore whether TWIST1 is a prerequisite for EGF induced EMT in EGFR mutated lung cancer cells, we confirmed that long time EGF treatment (10 days) did not generate an EMT in HCC827 TWIST1 negative cells." (PMID 22272264, 2012). "Early reports appeared on the experience of lung cancer patients with EGFR mutations." (PMID 22685658, 2012). "The presence of other genetic alterations together with EGFR activating mutations in lung cancer cells could lead to EGFR TKI resistance by promoting cell survival in the face of EGFR inhibition." (PMID 22970367, 2012). "There have been several studies examining associations between EGFR polymorphisms and clinical outcome of lung cancer therapy; however, the underlying mechanism is largely unknown." (PMID 23226726, 2012). "Mutations of these two residues to polar ones (L834R and L837E) have been found in lung cancer patients, and the EGFR kinase domain carrying the L834R mutation displays a substantially increased activity, underscoring the importance of the two residues in the inhibition of the kinase activity." (PMID 23028635, 2012). "At the molecular level, non-small cell lung cancer in never smokers are more likely to have mutations in epidermal growth factor receptor (EGFR) tyrosine kinase and patients harboring EGFR mutations show good response to its inhibitors compared to patients with tobacco-associated lung cancer." (PMID 22928112, 2012). "We examined whether TWIST1 reactivation was associated with mutated EGFR in human lung carcinoma cell lines and related to a mesenchymal phenotype." (PMID 22272264, 2012). "Additionally, mutations of exons 18 and 20, which can harbor upto 15% of EGFR-mutations in lung cancer, cannot be analyzed in this way." (PMID 22132735, 2011). "In addition, the Scorpion Amplified Refractory Mutation System (SARMS) technology can be used to detect EGFR mutations in serum genomic DNA or circulating lung-cancer cells." (PMID 21444946, 2011). "Examples include EGFR mutation analysis in lung cancer and HER-2 in breast cancer." (PMID 22188997, 2011). "A promising result regarding lung cancer was the discovery that somatic activating mutations in the tyrosine kinase domain of the EGFR gene identified a subset of non-small cell lung cancer (NSCLC) patients that may respond to tyrosine kinase inhibitors." (PMID 21575252, 2011). "Mutation of the EGFR proto-oncogene is found in 10% to 20% of lung carcinomas (mostly adenocarcinomas) and nearly 90% of lung cancer-specific EGFR mutations comprise a leucine-to-arginine substitution at position 858 (L858R) and deletion mutations in exon 19 (delE746-A750)." (PMID 21444946, 2011). "While EGFR is activated by phosphorylation in 20% of cervical cancers, no mutations have been demonstrated so far to our knowledge, which is very different from lung cancer which harbours close to 20% (559/2880) mutations in the EGFR kinase domain." (PMID 22091418, 2011). "First-line gefitinib for patients with advanced nonsmall cell lung cancer who are selected on the basis of EGFR mutations improves progression-free survival, with acceptable toxicity, compared with standard chemotherapy, although it failed to prolong overall survival." (PMID 22191026, 2011).
lung cancer (continued). "Taking these examples as precedent, it is reasonable to hypothesize that germ-line mutations in the EGFR gene could be involved in lung cancer pathogenesis, and probably in other tumours in whose development EGFR deregulation can play a role." (PMID 21575252, 2011). "Lung cancers harboring the EGFR mutations are remarkably sensitive to EGFR tyrosine kinase inhibitors such as gefitinib or erlotinib, which has been a very important discovery impacting the clinical treatment of lung cancer." (PMID 24212941, 2011). "IHC is a standardized assay of simple methodology and high sensitivity and specificity, and the development of specific antibodies against EGFR mutation proteins might be useful for the diagnosis and treatment of lung cancer." (PMID 21167064, 2010). "Current strategies to treat cancer is mainly driven by identifying genetic changes (e.g., EGFR, epidermal growth factor mutations in lung cancer), but recent evidence suggests that epigenetic plasticity together with genetic lesions also drives tumor progression." (PMID 21085674, 2010). "Investigation of EGFR mutations in lung cancers has become a pivotal research paradigm that has begun to unlock the utility of mutations in predicting clinical outcomes, selection of patients for therapies (EGFR-TKIs), and predicting response/resistance to these therapies." (PMID 20942962, 2010). "Immunohistochemistry (IHC) with mutation-specific antibodies may be an ancillary method of detecting EGFR mutations in lung cancer patients." (PMID 21167064, 2010). "Likewise, drugs such as erlotinib or gefitinib work only in lung cancer patients with specific mutations in the epidermal growth factor receptor (EGFR) gene." (PMID 24281040, 2010). "Specifically, EGFR and c-Met co-associate in normal human hepatocytes and lung cancer cell lines." (PMID 20624308, 2010). "With the EGFR/PI3K signaling cascade being one of the most frequently mutated pathways in lung cancer, we speculated that combined inhibition of EGFR- and PI3K/mTOR-signaling might be effective in our cell line panel of NSCLC cells." (PMID 20111714, 2010). "The development of EGFR tyrosine kinase inhibitors for clinical use in non-small cell lung cancer and the subsequent discovery of activating EGFR mutations have led to an explosion of knowledge in the fields of EGFR biology, targeted therapeutics and lung cancer research." (PMID 21165163, 2010). "EGFR mutations are likely not limited to lung cancer and pervasive in other cancer." (PMID 20942962, 2010). "Our studies were initially driven by the hypothesis that in lung cancer cell lines, tyrosine phosphorylation patterns would be related to the state of EGFR signaling, and in particular to EGFR mutation status." (PMID 20976048, 2010). "Chinese patients of lung cancer have a higher frequency of EGFR mutations than American patients." (PMID 20843324, 2010). "Examples include immunofluorescence for IGF-1R and the DNA damage response marker, gH2AX, in Phase I studies, EGFR and HER2 status in breast cancer, FISH for PTEN and FISH and RNA for TMPRSS2-ERG fusion in prostate cancer, and genotyping for EGFR mutations in lung cancer." (PMID 20838621, 2010). "Since East Asians with lung cancer have a higher frequency of EGFR and MET mutations in lung tumors, we also determined mutations in EGFR and MET in the same Taiwanese cohort samples and compared the results with the observed c-CBL alterations (LOH and/or mutations)." (PMID 20126411, 2010). "However, other molecular correlates of response to EGFR-targeting agents have been described for lung cancer and colorectal cancers including EGFR gene amplification, other somatic tumor mutations and patient genetic variations." (PMID 19636423, 2009). "However, despite the clinical importance, the underlying molecular mechanism by which EGFR signaling regulates lung cancer development remains poorly understood." (PMID 19702827, 2009).
lung cancer (continued). "The recent discovery of lung cancer mutations in the EGFR kinase domain and their differential sensitivity to EGFR inhibitors have suggested that genetic alterations may be associated with structural changes, rendering tumors sensitive to selective inhibitors." (PMID 19834613, 2009). "An activating mutation in the activation loop of the EGFR kinase domain, L858R (also identified as Leu834 in a different numbering of the EGFR sequence) is among most frequent mutations in lung cancer, amounting to more than 40% of EGFR mutations in this cancer category." (PMID 19714203, 2009). "A cocktail of MAP assays for the common 15/18 bp deletions, together with a Bi-PAP-A assay for the common L858R mutation, could detect about 70–80% of EGFR mutations constituting about 10% of total lung cancers." (PMID 19789704, 2009). "A family with a germline missense mutation in EGFR has a dramatic lung cancer phenotype." (PMID 19789704, 2009). "Furthermore, predictive value of low represented K-Ras mutations need to be assessed in lung cancer patients treated by targeted anti-EGFR treatments, to optimise such treatments in NSCLC patients." (PMID 19293811, 2009). "Moreover, the function of EGFR mutations in survival of lung cancer patients and clinical respones to gefitinib has been reported." (PMID 19702827, 2009). "Moreover, mutations in EGFR kinase domain have been shown to mediate STAT3 activation by IL-6 production in human lung carcinomas, suggesting that EGFR-like STAT3 activation can be mediated by IL-6R or GP130 receptors in an autocrine manner." (PMID 19088723, 2009). "Furthermore, EGFR exon 13 R521K variant has been already described in other EGFR expressing tumors, such as gliomas and lung cancer." (PMID 18544172, 2008). "Lung cancer with EGFR mutation was shown to be a specific clinical entity." (PMID 18549475, 2008). "Approximately 10–30% of lung carcinoma contain EGFR mutations." (PMID 18542074, 2008). "In addition, the EGFR haplotypes composed of five polymorphisms were estimated, and their frequency distributions in the lung cancer cases and controls were compared." (PMID 17956637, 2007). "Therefore, the effect of the EGFR 181946C>T genotype on the risk of lung cancer was estimated according to the histological type of lung cancer." (PMID 17956637, 2007). "To test this hypothesis, we performed a case-control study to investigate the association between EGFR genotypes/haplotypes and the risk of lung cancer." (PMID 17956637, 2007). "In this study, we tested the hypothesis that polymorphisms in the EGFR gene can affect the risk of lung cancer in the general population." (PMID 17956637, 2007). "To test this hypothesis, we evaluated the potential association of five EGFR polymorphisms (127378C>T, 142285G>A, 162093G>A, 181946C>T and 187114T>C) and the risk of lung cancer." (PMID 17956637, 2007). "The models could help accelerate the development of improved therapies for patients with lung cancers harboring EGFRT790M alone or in conjunction with drug-sensitive EGFR kinase domain mutations." (PMID 17726540, 2007). "Several studies suggest that activating mutations in EGFR are predictive of whether inhibitors, such as Iressa, would be effective in patients with lung cancer." (PMID 17875215, 2007). "The association between the EGFR 181946C>T genotypes and the risk of lung cancer was further examined after stratification according to gender, age, smoking status, and histologic types of lung cancer." (PMID 17956637, 2007). "Moreover, because genetic polymorphisms often vary between different ethnic groups, further studies are needed to clarify the association of the EGFR polymorphisms with the risk of lung cancer in diverse ethnic populations." (PMID 17956637, 2007). "Polymorphisms in Epidermal Growth Factor Receptor (EGFR) gene may influence EGFR production and/or activity, thereby modulating susceptibility to lung cancer." (PMID 17956637, 2007).